SNORD118 (small nucleolar RNA, C/D box 118)
Synonyms: U8; LCC
Gene: Small nucleolar RNA gene on chromosome 17 (8,173,452 to 8,173,588, reverse strand). Ensembl gene ENSG00000200463.
Gene Ontology:
Biological process: RNA processing
Cellular component: nucleolus
Diseases named in the same sentence as SNORD118 in open-access papers:
SNORD118 is named in the same sentence as 11 diseases in open-access papers, as found by Europe PMC text mining. Sharing a sentence is not in itself a finding about the gene and the disease. The quoted sentences say what the papers report.
Leukoencephalopathy (5 papers, 2018 to 2024). This term describes abnormality of the white matter of the cerebrum resulting from damage to the myelin sheaths of nerve cells. "SNORD118 is involved in regulation of ribosome biology and associated with the hydrocephalic phenotype of Labrune syndrome, characterized by leukoencephalopathy, intracranial cysts, and calcification." (PMID 38439105, 2024). "An additional member of the RNA panel, SNORD118, may play a critical role in ribosomal function and protein translation: a study of 40 patients having leukoencephalopathy with calcifications and cysts identified bi-allelic mutations in SNORD118." (PMID 30473705, 2018). "This phenomenon, first described in the context of thrombocytopenia-absent radius (TAR) syndrome, has only rarely been invoked since, e.g., SNORD118-related cerebral microangiopathy leukoencephalopathy with calcifications and cysts, and TXNL4A-related Burn-McKeown syndrome." (PMID 32552793, 2020). "Leukoencephalopathy with calcifications and cysts (LCC; also known as Labrune syndrome, OMIM #614,561) is a rare, autosomal recessive disorder caused by biallelic mutations in small nucleolar RNA, C/D Box 118 (SNORD118), a non-protein-coding, small nucleolar RNA gene on chromosome 17p13." (PMID 37847489, 2024).
leukemia (4 papers, 2024 to 2025). A malignant (clonal) hematologic disorder, involving hematopoietic stem cells and characterized by the presence of primitive or atypical myeloid or lymphoid cells in the bone marrow and the blood. "Moreover, in a mouse model that carries the two most prevalent gene mutations in AML, Npm1c and Flt3-ITD, we observed an upregulation of SNORD118 expression as well as the expression of Rnu3b family members (mouse orthologs of human SNORD3A) upon leukemia induction by double mutations (DM)." (PMID 38942785, 2024). "For instance, in leukemia stem cells, SNORD118 and SNORD3A enrich and display a high frequency of trans‐association with chromatin." (PMID 40884233, 2025). "Taken together, these data indicated the importance of SNORD118 and SNORD3A in leukemia maintenance and the potential suitability of SNORD118 as therapeutic vulnerability since healthy hematopoiesis was less affected upon its loss." (PMID 38942785, 2024). "Of note, our work revealed novel roles of SNORD118 and SNORD3A as chromatin-association factors that are essential for the maintenance of leukemia cell growth." (PMID 38942785, 2024). "To uncover how SNORD118 essentializes leukemia cells propagation, we performed a series of analyses on cell differentiation, cell cycle and apoptosis upon shRNA-mediated SNORD118 depletion in MV4-11 cells." (PMID 38942785, 2024). "Suppression of SNORD118 and SNORD3A impaired leukemia cell proliferation and colony forming capacity in AML cell lines and primary patient samples." (PMID 38942785, 2024). "The transcription of SNORD118 and SNORD3A was increased upon leukemia transformation and enriched in leukemia stem cells, but decreased during myeloid differentiation." (PMID 38942785, 2024). "Besides, SNORD118 knockdown did not alter ATRA-induced neutrophil differentiation in HL-60 leukemia cells." (PMID 38942785, 2024).
breast carcinoma (2 papers, 2024). "Notably, in the literature, it was found that SNORD44 is downregulated in breast cancer and associated with a poor prognosis, whereas SNORD118 was upregulated in breast cancer and its depletion inhibited tumorigenicity of breast cancer cells in vivo and in vitro." (PMID 38534323, 2024). "The functional importance of SNORD118 and SNORD3A in tumorigenesis has also been reported in lung cancer and breast cancer cells." (PMID 38942785, 2024).
lung carcinoma (2 papers, 2020 to 2024).
craniosynostosis (1 paper, 2024). Craniosynostosis is defined as the premature fusion of one or more cranial sutures leading to secondary distortion of skull shape resulting in skull deformities with a variable presentation. "Knocking out Snord118 led – ultimately – to cranial suture growth and craniosynostosis defects." (PMID 39834390, 2024).
cancer (2 papers, 2020 to 2024). A tumor composed of atypical neoplastic, often pleomorphic cells that invade other tissues. "However, their roles in these cancers were primarily associated with pre-rRNA processing and rRNA maturation, which are well-established functions of SNORD118 and SNORD3A in mammalian cells." (PMID 38942785, 2024). "Nevertheless, both SNORD3A and SNORD118 directly contribute to lung tumorigenesis by promoting ribosome production necessary to maintain cell growth and the high proliferative rate of cancer cells." (PMID 32111002, 2020). "Hence, SNORD3A and SNORD118 do have key functions in maintaining human ribosome biogenesis in cancer cells." (PMID 32111002, 2020).
tumor (2 papers, 2023 to 2024). "The invasion of SNORD3A knockout tumor cells significantly decreased and the tumorigenicity of cancer cells completely disappeared when SNORD118 was completely knocked out." (PMID 37492704, 2023). "Since eribulin induced upregulation of SNORD44 and downregulation of SNORD118, eribulin could exert its anti-tumor roles also by affecting the expression of these snoRNAs." (PMID 38534323, 2024).
SNORD118 also shares sentences with these, for which no sentence is quoted: Labrune syndrome (4 papers); calcification (2); Burn-McKeown syndrome (1); liver cancer (1).